CD74 (CD74 molecule)
Diseases named in the same sentence as CD74 in open-access papers (continued):
Sharing a sentence is not in itself a finding about the gene and the disease.
tumor (continued). "In accordance with a common B-lymphomagenic potential of the viruses applied for tumor induction of Cd74-targeted tumors and the tumor target tissue, no general pattern of rearrangements in the TCRβ chain was detected indicating that these tumors indeed were not in general of T-cell type." (PMID 20416035, 2010). "Additionally, in tumor biopsies, we found that tumor cells displayed strong CD74 staining, while normal ciliated epithelial cells showed no staining, which suggests that expression of this molecule in epithelial cells is related to tumor development or progression." (PMID 39001552, 2024). "Besides, we could not show the significant association between CD74 and MIF expressions in tumor tissues, including tumor-infiltrating immune cells and sCD74 and MIF levels in paired sera, respectively." (PMID 35121729, 2022). "We then discussed the effects of other cell types on epithelial cells in tumor tissue, and the results indicated that immune cells could regulate epithelial cells through specific ligand–receptor pairs, such as TNFSF14-TNFRSF14, MIF-(CD74+CD44), IFNG-(FINGR1+IFNGR2), CXCL12-ACKR3, and CXCL11-ACKR3." (PMID 36569924, 2022). "Given that expression of both CD74 and PD-L1 can be induced by proinflammatory cytokines such as IFNγ, it is possible that the association we found simply reflects the presence of cytokines produced by activated CD8+ T cells in the tumor microenvironment, rather than a functional relationship." (PMID 34944801, 2021). "In addition, CD74 shRNA increased U87 cells response to temozolomide and blockade of CXCR4, through the small molecule antagonist AMD-3100 diminished intracranial growth and proliferation of the tumor and augmented apoptosis, due to the decreased activation of ERK-1 and 2 and AKT." (PMID 29707160, 2018). "Many studies have furthermore demonstrated CD74 expression in various non-hematological cancers including gastric, colon, lung, and renal epithelial cancers, and moreover has the elevated expression level in several cancers served as a marker for tumor progression and/or poor clinical outcome." (PMID 20416035, 2010). "In this research, no statistical differences in the expression levels of MIF, CD74, and CXCR4 were found between tumor and normal groups." (PMID 40066443, 2025). "Furthermore, widespread co-localization of MIF-(CD74+CXCR4) was observed in spatial transcriptomics, suggesting that the MIF signaling pathway may be a key mechanism through which MVI_Scissor+ malignant cells exert significant influence in the tumor microenvironment." (PMID 39176099, 2024). "For example, the CD74-COPA pair, from B cells to epithelial cells, was highly expressed in tumor group, while it is not observed in normal group." (PMID 37908350, 2023). "The functional role of CD74 is not well clarified, even though it is known to function in the molecular processing of MHC II, with a potential role in the anti-tumor immune response." (PMID 33925387, 2021). "In a follow-up study, infiltrating M-MDSCs were shown to highly express the cognate MIF receptor, CD74, while G-MDSCs primarily express the non-cognate CXCR2 receptor and exhibit only minimal tumor infiltration." (PMID 33324425, 2020). "In this study, we have found an association between the expression of the follow proteins (STAT5, STAT3_pS727, BMP6, CD74, TFRC, INHA, and STAT5_pY694) involved in iron homeostasis and the type of tumor tissue (breast cancerous vs. non-cancerous)." (PMID 28216608, 2017). "The co-expression of MIF and CD74 seems to be important in tumorigenesis, and either MIF or CD74 alone might not be strong tumor biomarkers." (PMID 33542244, 2021). "Interestingly, both the solid tumor mass and the 11/12 identified disseminated tumor cells (DTCs and DTC cluster) in CSF were negative for both CD74 and CD44 expression." (PMID 34209696, 2021).
cancer (195 papers, 2009 to 2026). A tumor composed of atypical neoplastic, often pleomorphic cells that invade other tissues. "As the disease advanced, Fib_FBLN1+ fibroblasts—associated with tissue repair and homeostasis gradually transitioned into cancer-associated fibroblasts (CAFs), including Fib_POSTN+, Fib_CD74+, and Fib_CXCR4+ subpopulations." (PMID 40948762, 2025). "CD74 was found to be effective (the area under the curve [AUC] > 0.7) in predicting nine cancers, indicating a high diagnostic value." (PMID 38582956, 2024). "CD74 has been associated with cancer progression, proinflammatory immune response, has been implicated in regenerating tissues, and is considered a monocytic/macrophagic marker within the myeloid branch of the hematopoietic system." (PMID 38582086, 2024). "MIF and CD74 have been implicated in the mechanisms of the development of various cancers, including non-small-cell lung cancer, prostate cancer, head and neck squamous cell carcinoma, and brain tumors." (PMID 38730725, 2024). "Filtering compounds using the cMap tool caused the same transcriptional alterations as increased CD74 expression in nine cancer cell lines and identified the top 20 compounds predicted to activate CD74." (PMID 38582956, 2024). "The c04_CXCL12 subgroup displayed characteristics of both antigen‐presenting cancer‐associated fibroblasts (apCAFs), marked by CD74 and HLA‐DRA, and immune‐related cancer‐associated fibroblasts (iCAFs), indicated by CXCL14 and CXCL12." (PMID 39716897, 2024). "MIF is overexpressed in various cancers, including lung cancer, osteosarcoma, metastatic melanoma, and many others; CD74 expression and overexpression are also associated with diverse cancers." (PMID 38730725, 2024). "More precisely, MIF downregulated the interaction between cancer-associated fibroblasts and immune cells including B cells, DCs, myeloid derived suppressor cells, monocytes, NK cells, and T cells via the CD74/CD44 and CXCR2/CXCR4 signaling pathways." (PMID 38638429, 2024). "Significantly, CD74 was found to be associated with cancer immunity and acted as a biomarker of the infiltration of M1 macrophages." (PMID 38582956, 2024). "It has also been shown that MIF and CD74 expression are closely associated with patient outcomes in many types of cancer, and it is widely suggested that both molecules are promising candidate therapeutic targets." (PMID 38730725, 2024). "Regression and KM analyses of prognosis prediction in pan-cancer showed that increased expression of CD74 was associated with prolonged survival in patients with BRCA, CESC, LUAD, MESO, SARC, SKCM, and UCEC, suggestive of a protective role in these cancers." (PMID 38582956, 2024). "Previous studies have implicated CD74 as a regulatory factor of cell proliferation and metastasis in a variety of human cancers." (PMID 39113235, 2024). "As CD74 is implicated in a diverse range of cancers, it is important to discover novel and effective ways to meet the challenges associated with this protein." (PMID 37958963, 2023). "CD74 was demonstrated to be upregulated in various types of cancer and associated with abnormal cell growth and metastasis." (PMID 36160439, 2022). "Of interest, CD74 is upregulated in various forms of cancer and is associated with proliferative and metastatic potential but is downregulated in several cancers, including OS." (PMID 34957096, 2021). "We have shown CD74 is important in proliferation of gastric carcinoma cells while others have suggested this in other inflammation-associated cancers such as prostate and renal cancers." (PMID 24887129, 2014). "Taking into account the frequent CD74 expression in cancers together with the impaired Fas signaling associated with chemoresistance, we extrapolate that CD74 also contributes to chemoresistance." (PMID 25304249, 2014). "In this regard, distinct expression patterns of these CD74 forms may predispose patients to substantial differences in cancer progression and survival." (PMID 35121729, 2022).
cancer (continued). "Soluble CD74 (sCD74) has been identified in sera of inflammatory diseases and implicated in their pathophysiology; however, few relevant data are available in the context of cancer." (PMID 35121729, 2022). "Thus, this indicates that there is certainly cohort- and readout-based uncertainties in determining the clinical significance of CD74 expression in cancer cells and associated immune cells." (PMID 34944801, 2021). "Moreover, the CD74 gene, encoding the molecular chaperone invariant chain, was also decreased in the cancer group." (PMID 28350008, 2017). "Aberrant expression of CD74 in both hematologic and solid tumors reflects its adaptability to oncogenic pressures and its role in shaping the immune landscape of cancer." (PMID 41597203, 2026). "In the context of cancer, dysregulation of these mechanisms can shift CD74′s role toward protumorigenic signaling, underscoring its importance as a therapeutic target, which we discuss in the next chapters." (PMID 41597203, 2026). "CD74 has attracted significant interest as a molecular tool in vaccine engineering for cancer immunotherapy." (PMID 41597203, 2026). "Beyond its role in adaptive immunity as a chaperone for MHC-II molecules during antigen processing and presentation to CD4+ T cells in steady-state, CD74 has emerged as a signaling receptor with key implications in cancer biology." (PMID 41597203, 2026). "In parallel with CD74-targeted cancer therapies, humanized monoclonal antibodies that neutralize MIF itself are also under development." (PMID 41597203, 2026). "Collectively, these innovations highlight CD74′s value as a biotechnology tool for cancer vaccine optimization." (PMID 41597203, 2026). "This dual role illustrates the complex, context-dependent nature of CD74′s contribution to cancer biology." (PMID 41597203, 2026). "These cells expressed pro-inflammatory genes, such as Cd74, S100a8, and S100a9, which have been shown to contribute to the progression of various cancer types." (PMID 39425000, 2025). "Blocking CD74 has been shown to inhibit MDA-MB-231 cell proliferation, highlighting the role of MIF/CD74 signaling in driving the growth of both non-invasive and invasive cancer cells." (PMID 41159021, 2025). "Targeting the proteolytic processing of CD74 has emerged as a rational therapeutic strategy across cancer, autoimmune, and inflammatory diseases." (PMID 41439980, 2025). "This was characterized by high expression of macrophage migration inhibitory factor (MIF) in cancer cells, which signaled to B cells expressing the CD74 and CXCR4 receptors." (PMID 41249133, 2025). "This pattern coincided with the upregulation of key markers associated with cancer stemness (CD133, CD44) and metastasis/invasion (MMP7, CD74), highlighting FXYD5 as a potential driver of malignant progression." (PMID 41457101, 2025). "Further analyses verified that macrophages mainly interacted with fibroblasts via MIF-ACKR3 and HBEGF-EGFR, and exhibited enhanced interactions with epithelial and cancer cells through MIF-(CD74 + CD44)." (PMID 41150752, 2025). "CD74 expression levels are significantly upregulated in most cancers than in normal tissues; CD74 supports the accumulation and function of regulatory T cells in tumors." (PMID 41439980, 2025). "The activation of these transcription factors endowed TLS‐resident CD74+ B cells with enhanced immunological competence, highlighting their potential as prognostic biomarkers and therapeutic targets in cancer immunotherapy." (PMID 41111459, 2025). "In this study, combined with a multi-omics study, CD74 levels were significantly upregulated in most cancers relative to normal tissues and were found to be predictive of prognosis." (PMID 38582956, 2024). "While a comprehensive discussion of MIF and CD74 in cancer is outside the scope of this work, the interested reader is referred to several excellent reviews on this topic." (PMID 38730725, 2024).
cancer (continued). "Taken together, our results suggest that the gene expression level of CD74 serves as a potential predictor in multiple cancer types for anti-PD-1/CTLA-4 immunotherapy." (PMID 38280003, 2024). "We found that CD74 is correlated with aberrant elevation of cancer hallmarks, but its biological impacts remain elusive." (PMID 39056676, 2024). "This showed close correlations between CD74 levels and the expression of at least one methyltransferase in the majority of cancer types, apart from DLBC, ESCA, PCPG, and UCS." (PMID 38582956, 2024). "CD74 function was also evaluated in terms of DNA damage and repair processes, cancer immunity, and epigenetic modifications." (PMID 38582956, 2024). "CD74 levels were also associated with TMB, MSI, HRD, aneuploidy, neoantigen, DNA repair, cancer stemness, DNA methylation, and chemoresistance." (PMID 38582956, 2024). "Consistently, we confirmed that inhibition MIF in cancer cells and CD74 in microglia promoted M1 polarization, showing upregulated level of CD86 fluorescence intensity and proportion of CD86 + cells." (PMID 38685050, 2024). "Previous studies have shown that the expression of CD74 on immune cells modulates the activity of cancer cells." (PMID 38582956, 2024). "COPA affects cancer therapeutic response through the remodeling of immune microenvironment in a variety of cancers, and activation of CD74-APP/COPA/MIF on the surface of B cells facilitates the suppressive immunomodulatory effects of M2 macrophages and Tregs." (PMID 39422621, 2024). "Patients with high CD74 gene expression and protein expression (ICP ≥ 10%) effective clinical response and prolonged survival following AK104 treatment, suggesting that CD74 has potential predictive performance in AK104 cancer therapy." (PMID 38280003, 2024). "As a pleiotropic protein, MIF plays an important role in cancer growth, inflammation, and immune response by activating the signaling pathways of the CD74 and CXC chemokine receptors." (PMID 38924362, 2024). "The type II transmembrane protein CD74 has been found to be abnormally upregulated in a variety of cancers." (PMID 38582956, 2024). "Throughout the five fusions expressed in cancer patients, all retain the transmembrane domain of CD74 that many times makes up for the transmembrane domain that biologically occurs in the fusion partner before splicing occurs." (PMID 37958963, 2023). "The data on CD74 fusions offers insight for improved therapy plans for cancer patients and the development of additional methods for early detection to improve treatment success and patient survival." (PMID 37958963, 2023). "The results revealed that the cancer cell subclusters c8_TOP2A, c9_HMGB2, c12_MKI67, and c13_TK1 were dominantly in a cycling state, while c1_TCN1, c2_CD74, c3_CD24, c5_CEACAM6, and c10_SAT1 were mainly in a quiescent state." (PMID 36529697, 2023). "In a recent study, CD74 was shown to shift the localization of the tumor suppressor Scribble as well as down‐regulate the expression of the protein in cancer cells." (PMID 37081824, 2023). "CD74 was significantly upregulated in cancer cells in GGN and was strongly associated with APP and COPA in alveolar epithelial cells, ciliated cells, and endothelial cells." (PMID 37745301, 2023). "Milatuzumab, a novel immunotherapeutic drug targeting CD74, has shown promising results in clinical trials for cancer treatment." (PMID 38099290, 2023). "As a result, much effort has been expended in trying to explore differential expression of CD74 or TSPAN7 in cancer cell strains, ignoring the influence of immune infiltration." (PMID 36911401, 2023). "This particular property of CD74 has been successfully used for targeted drug delivery to cancer cells." (PMID 37081824, 2023). "The receptor CD74 was recently identified as a regulator of oncogenic properties in various cancers." (PMID 37629174, 2023). "The contribution of CD74 to cancerogenesis seemed to vary with the type of cancer and stage of the disease." (PMID 37147569, 2023).
cancer (continued). "EN0 showed higher expression of ACKR1 (logFC = 1.2), carcinoma-associated genes RACK1 (logFC = 0.7) and CD74 (logFC = 0.8)." (PMID 38328306, 2023). "DCs, especially CD1C+_B dendritic cell_3, played a critical role in cancer progression probably through CD74 signaling." (PMID 35769782, 2022). "The top outgoing signaling from epithelial cancer cells to CAFs (communication probability > 0.10) showed interactions between MIF (cancer cells) and CD74 + CD44 (CAFs) or MDK (cancer cells) and NCL/SDC2/LRP1 (CAFs)." (PMID 36352420, 2022). "We observed top-ranking ligand-receptor pairs of macrophage migration inhibitory factor (MIF) in cancer cells and (CD74+CD44) in macrophages." (PMID 36248860, 2022). "CD1C+_B dendritic cell_3 played a key role in tumorigenesis and cancer progression possibly through CD74-MIF." (PMID 35769782, 2022). "In this study, we found that patients in the low-risk subgroup had higher expression of common immune checkpoint molecules such as PD-1, PD-L1, LAG3, CTLA-4, PD-L2, and CD74, which are commonly expressed in human cancer." (PMID 35996170, 2022). "Upon binding CD74 on the cell surface, anti-CD74 monoclonal antibodies become rapidly internalized, pointing to the strong potential of targeting the CD74 antigen for cancer therapy." (PMID 33430210, 2021). "IFNγ is known to stimulate upregulation of CD74 protein in many cell types, including in cancer cells." (PMID 34944801, 2021). "LE-KLK3 and LE-KLK4 both expressed macrophage inhibitory factor (MIF), a macrophage survival, activation and recruiting factor, with its receptor CD74 expressed by all prostate MNPs, and this interaction was attenuated in cancer samples." (PMID 34936871, 2021). "CD74 is a transmembrane protein normally expressed in immune cells, and aberrantly expressed in cancer cells." (PMID 34944801, 2021). "The protein CD74 is expressed on antigen-presenting cells and reports showed that CD74 expression serves as a prognostic factor in many cancers." (PMID 33552736, 2021). "Our results are consistent with the group of previous studies that showed a survival benefit in cancer patients with high CD74 expression and higher immune infiltration." (PMID 34944801, 2021). "Cancer biology studies have shown that CD74 bound to MIF initiates survival and cell proliferation through the phosphoinositide-3-kinase (PI3K)/protein kinase B (Akt) and extracellular signal-regulated kinase (ERK) signaling pathways." (PMID 32004754, 2020). "The role of CD74 in other disease processes, antigen presentation, and cancer has been well-reviewed elsewhere." (PMID 32655566, 2020). "There are no integration sites in chromosomes 21, 22, and X. Only five genes of the many associated with MCPyV integration, namely SF3B1, TLX3, CD74, MYC, and KMT2D, are cancer-linked genes listed in the COSMIC database." (PMID 32878339, 2020). "Because of its rapid internalization, association with major histocompatibility complex class II and restricted expression by normal cells, CD74 can deliver cytotoxic drugs inside cancer cells." (PMID 31544840, 2019). "Different drugs targeting MIF and its main receptor CD74 are in clinical development in many diseases, including cancer." (PMID 29875777, 2018). "Because CD74 and CD44 are both involved in MIF-mediated signalling, CD74 is considered a potential therapeutic target in cancer." (PMID 29190904, 2017). "Conversely, inhibition of MIF/CD74 signalling axis elevated ROS rendering cancer cells vulnerable to oxidative stress-induced cell death." (PMID 28114961, 2017). "In accordance with our recent study, DIO1 expression resulted also in suppression of TGFBI, and several other proteins (e.g. PODXL, CD74) that promote RCC progression or act as oncogenic proteins in other cancers (e.g. FMNL2, APBB1IP, ASAP1, and LRRFIP1)." (PMID 29272308, 2017).